RNPC3 (RNA binding region (RNP1, RRM) containing 3)
Description:
Participates in pre-mRNA U12-dependent splicing, performed by the minor spliceosome which removes U12-type introns. U12-type introns comprises less than 1% of all non-coding sequences. Binds to the 3'-stem-loop of m(7)G-capped U12 snRNA.
Synonyms: KIAA1839; RBM40; RNP; SNRNP65; FLJ20008; CPHD7; IGHD5
Tractability: PROTAC: ubiquitination databases record sites on it; its protein half-life has been measured.
Gene: Protein-coding gene on chromosome 1 (103,525,675 to 103,555,239, forward strand). Ensembl gene ENSG00000185946.
Subcellular location: Nucleus
Subcellular location (Human Protein Atlas): Nucleoplasm
Pathways (Reactome):
Metabolism of RNA: mRNA Splicing - Minor Pathway
Gene Ontology:
Molecular function: nucleic acid binding; RNA binding
Biological process: mRNA splicing, via spliceosome; RNA splicing
Cellular component: nucleoplasm; nucleus; U11/U12 snRNP; U12-type spliceosomal complex
Genetic constraint (gnomAD): Loss-of-function variants: 10 observed, 16.29 expected, observed/expected ratio (o/e) 0.61, 90% interval 0.38 to 1.04. The upper end of that interval is the gene's LOEUF score, 1.04, which puts it in group 4 of 6, group 1 being the genes least tolerant of losing a copy. Missense variants: 228 observed, 224.38 expected, observed/expected ratio (o/e) 1.02, 90% interval 0.91 to 1.13. Synonymous variants: 95 observed, 88.77 expected, observed/expected ratio (o/e) 1.07, 90% interval 0.91 to 1.27.
Homologues: Orthologues: chimpanzee RNPC3 (99% identical), macaque RNPC3 (99% identical), pig RNPC3 (93% identical), dog RNPC3 (93% identical), guinea pig RNPC3 (91% identical), mouse Rnpc3 (89% identical), rat Rnpc3 (88% identical), rabbit RNPC3 (84% identical), tropical clawed frog rnpc3 (56% identical), zebrafish rnpc3 (53% identical), Drosophila melanogaster CG44249 (23% identical). Paralogues in human: RBM41 (18% identical).
Diseases named in the same sentence as RNPC3 in open-access papers:
RNPC3 is named in the same sentence as 133 diseases in open-access papers, as found by Europe PMC text mining. Sharing a sentence is not in itself a finding about the gene and the disease. The quoted sentences say what the papers report.
Autoimmunity (9 papers, 2018 to 2025). The occurrence of an immune reaction against the organism's own cells or tissues. "A direct pathophysiological link between RNA-PolIII antigen modification in tumor and autoimmunity is even suggested in this condition, as developed below (paragraph Anti-RNPC-3)." (PMID 30687318, 2018). "These anti-RNPC3 autoantibodies would possibly be indicative of cancer-induced autoimmunity in this subgroup of patients." (PMID 30687318, 2018).
systemic sclerosis (9 papers, 2007 to 2025). A chronic disorder, possibly autoimmune, marked by excessive production of collagen which results in hardening and thickening of body tissues. "From a medical standpoint, the detection of new autoantibodies, like anti-RNPC3, is becoming more and more important for improving the precision of diagnoses and improving the classification of outcomes in systemic sclerosis." (PMID 41155396, 2025).
lung carcinoma (5 papers, 2017 to 2025). "RNPC3 knockdown in human lung cancer-derived A549 cells also impairs cell proliferation and RNA-seq analysis reveals a robust and selective disruption to minor intron splicing and transcription-wide effects on gene expression." (PMID 40624356, 2025). "In addition, anti-RNPC3 antibody can be used as a marker for cancer scleroderma including lung cancer." (PMID 36386821, 2022).
pulmonary fibrosis (5 papers, 2008 to 2025). Chronic progressive interstitial lung disorder characterized by the replacement of the lung tissue by connective tissue, leading to progressive dyspnea, respiratory failure, or right heart failure. "Notably, anti-RNPC3 and anti-U1RNP positivity have also been associated with more significant pulmonary fibrosis, indicating a more fibrotic systemic phenotype." (PMID 41369419, 2025). "Anti-U11/U12 (RNPC-3) antibodies have been associated with ILD and pulmonary fibrosis." (PMID 37046475, 2023).
Intellectual disability (3 papers, 2020 to 2024). "Here, we report a second family with biallelic RNPC3 variants in three siblings with a growth hormone deficiency, central congenital hypothyroidism, congenital cataract, developmental delay/intellectual deficiency and delayed puberty." (PMID 32462814, 2020).
dwarfism (2 papers, 2018 to 2020). "RNPC3 has been linked to dwarfism in humans through defective pituitary somatotroph development and subsequent growth hormone deficiency." (PMID 33382735, 2020).
hypopituitarism (2 papers, 2022 to 2025). A condition of diminution or cessation of secretion of one or more hormones from the anterior pituitary gland. "Human RNPC3 mutations have been associated with hypopituitarism, growth hormone deficiency, and primary ovarian insufficiency—conditions that involve early ovarian failure and infertility." (PMID 40169226, 2025). "For example, mutations in the human RNPC3/65K are linked to hypopituitarism, growth hormone deficiency, and primary ovarian insufficiency." (PMID 40169226, 2025). "Thus, studying this protein may reveal both conserved and unique functions among homologous proteins and provide insights into how RNPC3 mutations are linked to diseases like hypopituitarism, growth hormone deficiency, and primary ovarian insufficiency in humans." (PMID 40169226, 2025).
hypothyroidism (2 papers, 2020 to 2023). Abnormally low levels of thyroid hormone. "WES analysis showed several variants in genes associated with short stature, GH deficiency and hypothyroidism including ACAN, GHR, RNPC3 and TSHR (Table-II)." (PMID 37680843, 2023). "Beside the observed variants in RNPC3, we found another variant in TSHR (c.154C>A) that might be linked to hypothyroidism status seen in the affected members of the studied family (IV-2 to IV-5)." (PMID 37680843, 2023).
leukemia (2 papers, 2020 to 2022). A malignant (clonal) hematologic disorder, involving hematopoietic stem cells and characterized by the presence of primitive or atypical myeloid or lymphoid cells in the bone marrow and the blood. "As has been found for other tyrosine kinase fusion proteins in leukemia, the coiled‐coil motifs derived from RNPC3 likely contribute to the dimerization or oligomerization of RNPC3‐JAK2 chimera, with consequent constitutive activation of the JAK2 kinase domain." (PMID 31885183, 2020).
lung adenocarcinoma (2 papers, 2022 to 2025). A carcinoma that arises from the lung and is characterized by the presence of malignant glandular epithelial cells. "Next, we carried out in vitro studies in a human lung adenocarcinoma-derived cell line, A549, with the aim of providing a mechanistic explanation of how reduced expression of RNPC3 causes a decrease in tumour burden in the various in vivo cancer models." (PMID 40624356, 2025). "In terms of RNPC3, little is known about the role of RNPC3 protein in human cancers, and some studies have shown that genes including RNPC3 can be used as diagnostic genes for lung adenocarcinoma." (PMID 36386821, 2022). "We also used the human lung adenocarcinoma cell line, A549, to show that reduced expression of RNPC3, and two other minor spliceosome-specific components, PDCD7 and U12 snRNA, causes minor intron retention and alternative splicing." (PMID 40624356, 2025). "We induced lung adenocarcinoma in KrasLSLG12D/+Rnpc3 WT and HET mice." (PMID 40624356, 2025). "Focusing the analysis on the cancer types investigated in our study, we found no RNPC3 mutations in 1950 AML samples, and only 0.1% (3 out of 3038) of HCC samples, 0.11% (6/5312) of lung adenocarcinomas and 0.32% (2/630) of gastric adenocarcinomas contain a mutation of unknown significance." (PMID 40624356, 2025).
ovarian failure (2 papers, 2022 to 2025). "In summary, two of three previously reported Spanish patients with RNPC3 variants developed ovarian insufficiency on follow-up, with elevated gonadotropins and small ovaries in the third." (PMID 34906446, 2022).
adenoma (1 paper, 2025). A neoplasm arising from the epithelium. "Having shown that Rnpc3 heterozygosity limits the growth of liver, lung and gastric hyperplasia/adenomas, we investigated whether hyperproliferative blood cancers were sensitive to Rnpc3 expression as well." (PMID 40624356, 2025). "Antral adenomas harvested from TMX-treated Tff1-CreERT2;Rnpc3lox/lox;Gp130F/F mice contained 50% less Rnpc3 mRNA than antral adenomas from TMX-treated Rnpc3lox/lox;Gp130F/F (no Cre-transgene) controls (Fig. EV2H)." (PMID 40624356, 2025). "However, there was a 35% decrease in the abundance of pERK1/2 protein in the adenomas of Rnpc3 HETs compared to Rnpc3 WT adenomas, indicating attenuation of the MAPK pathway in cells exhibiting heterozygous expression of RNPC3." (PMID 40624356, 2025).
gastric tumours (1 paper, 2025). "Using in vivo zebrafish and mouse cancer models, we show that heterozygous expression of Rnpc3, encoding a unique protein component of the minor spliceosome, restricts the growth and survival of liver, lung and gastric tumours without impacting healthy cells." (PMID 40624356, 2025).
Hydrocephalus (1 paper, 2023). Hydrocephalus is an active distension of the ventricular system of the brain resulting from inadequate passage of CSF from its point of production within the cerebral ventricles to its point of absorption into the systemic circulation. "In conclusion, we report novel mutations in known hydrocephalus genes in 18% of our PCH probands and propose three novel candidate genes: DNAH2, TIE1 and RNPC3 in a further 11%." (PMID 36859317, 2023).
lymphoid neoplasm (1 paper, 2020). A neoplasm composed of a lymphocytic cell population which is usually malignant (clonal) by molecular genetic and/or immunophenotypic analysis. "Our investigation provides the first reported example of RNPC3 rearrangement in lymphoid neoplasm." (PMID 31885183, 2020).
myelodysplastic syndrome (1 paper, 2017). A clonal hematopoietic disorder characterized by dysplasia and ineffective hematopoiesis in one or more of the hematopoietic cell lines. "Isolated Growth Hormone Deficiency type 1 (IGHD1;) is caused by mutations in the RNPC3 gene coding for the U11/U12-65K protein, and Myelodysplastic Syndrome (MDS;) by somatic mutations in the ZRSR2 gene coding for Urp protein involved in 3′ splice site (3′ss) recognition." (PMID 28549066, 2017).
non-small cell lung carcinoma (1 paper, 2022). A group of at least three distinct histological types of lung cancer, including non-small cell squamous cell carcinoma, adenocarcinoma, and large cell carcinoma. "In conclusion, low expression of RHEBL1 or high expression of RNPC3 was significantly associated with good prognosis in patients with non-small cell lung cancer." (PMID 36386821, 2022). "Overall, Protodioscin and Polyphyllin VI significantly promoted either low expression of RHEBL1 or high expression of RNPC3, causing patients with non-small cell lung cancer to exhibit a good prognosis." (PMID 36386821, 2022). "In conclusion, our findings strongly suggest that RHEBL1 and RNPC3 are potential targets for Polyphyllin VI and Protodioscin in the treatment of non-small cell lung cancer, and may also be candidate diagnostic genes for non-small cell lung cancer-related prognosis." (PMID 36386821, 2022). "Further testing revealed that low expression of RHEBL1 and high expression of RNPC3 in non-small cell lung cancer significantly improved the prognosis and prolonged life expectancy of cancer patients." (PMID 36386821, 2022). "In conclusion, the expression of RHEBL1 and RNPC3 significantly correlated with immune cells infiltrated by tumors in patients with non-small cell lung cancer." (PMID 36386821, 2022). "The results of bioinformatics analysis, molecular docking, flow cytometry and quantitative PCR suggest that RHEBL1 and RNPC3 may be potential targets for Polyphyllin VI and Protodioscin in the treatment of non-small cell lung cancer." (PMID 36386821, 2022). "This suggests a high probability of diagnosing non-small cell lung cancer with RNPC3 and RHEBL1." (PMID 36386821, 2022). "The intersection of the two was taken to screen five non-small cell lung cancer signature genes from the training sets GSE151103 and GSE33532: DOCK6, GPC2, RHEBL1, RNPC3, and PIWIL2." (PMID 36386821, 2022).
Obesity (1 paper, 2022). Accumulation of substantial excess body fat. "ACP cystic fluid caused growth retardation and an increased obesity index in mice, affected the expression of the Npy, Fgfr2, Rnpc3, Sst, and Pcsk1n genes that regulate growth and energy metabolism in hypothalamic neurons, and enhanced the cellular interaction of Agrp–Mc3r." (PMID 35525962, 2022).
ovarian carcinoma (1 paper, 2021). A malignant neoplasm originating from the surface ovarian epithelium. "Our splicing regulation network analysis showed some splicing factors might be correlated with prognosis-related AS events, including SPEN, SF3B5, RNPC3, LUC7L3, SRSF11 and PRPF38B, suggesting that these splicing factors could play crucial roles in ovarian cancer development." (PMID 34001978, 2021).
Potocki-Lupski syndrome (1 paper, 2021). "Recently, it has been reported that some patients with Potocki-Lupski syndrome or Prader-Willi syndrome have similar phenotypes as GHD patients, and recessive mutations in RNPC3 could also lead to the occurrence and development of GHD." (PMID 34589056, 2021).
cancer (33 papers, 2008 to 2026). A tumor composed of atypical neoplastic, often pleomorphic cells that invade other tissues. "Anti-RNPC3 antibody directed for the minor spliceosome complex is another autoantibody associated with cancer-associated SSc, particularly among triple negative (negative for ACA, ATA, and anti-RNAP III) SSc patients." (PMID 32085664, 2020). "Anti-RNPC3-positive SSc patients showed a 4-fold increased risk for cancer diagnosis within 2 years of SSc onset, and 89% of them possessed severe ILD at baseline." (PMID 32085664, 2020). "However, while the first study primarily focused on the characteristics of anti-RNPC-3+ patients and their association with cancer, the European study aimed to characterize the features of patients who tested positive vs. negative for that autoantibody." (PMID 40416966, 2025). "Disrupting the expression of the minor spliceosome component RNPC3 reduces the growth of oncogene-driven cancer cells in a broad spectrum of tumours." (PMID 40624356, 2025). "Our study complements these in vitro findings by demonstrating that heterozygous Rnpc3 expression is sufficient to reduce tumour burden in a variety of in vivo cancer models from zebrafish and mice, including those driven by mutant Kras oncogenes." (PMID 40624356, 2025). "To extend our findings to mammals, we introduced Rnpc3 heterozygosity into a variety of mouse cancer models and again observed significantly reduced tumour growth." (PMID 40624356, 2025). "This rarity of RNPC3 mutations suggests that cancers generally do not have alternative mechanisms to circumvent 65K deficiency." (PMID 40624356, 2025). "To test whether similar effects were observed in mouse models of cancer, we took Rnpc3 heterozygous mice and confirmed they exhibited a 50% decrease in Rnpc3 mRNA by RT-qPCR in two organs of interest, lung and stomach." (PMID 40624356, 2025). "These experiments showed that heterozygous expression of Rnpc3 is sufficient to markedly restrict the growth and proliferation of cancers driven by a variety of pro-proliferative, pro-survival pathways (KRAS/MAPK and STAT3), without any impact on healthy tissues." (PMID 40624356, 2025). "Our data show that a 70% depletion in the levels of mRNA transcribed from the RNPC3 locus in A549 cells results in the accumulation of aberrant MIG transcripts, changes in the expression of genes typically enriched in cancer cells and impaired growth and survival (EV5, and EV6)." (PMID 40624356, 2025). "Little is known about the function of RNPC3 protein in human cancer, and no RNPC3 gene abnormality has ever been reported in hematological malignancies." (PMID 31885183, 2020). "Recent studies have identified in “triple negative” scleroderma patients with cancer (patients without anti-centromere, anti-scl70 and anti-RNA-PolIII antibodies), a new autoantibody that targets RNPC-3." (PMID 30687318, 2018). "For example, if we had focused more strongly on a subset of our in vivo cancer models, we may have been successful in demonstrating a formal link between Rnpc3 heterozygosity and aberrant minor splicing, which is absent from our current study." (PMID 40624356, 2025).
tumor (25 papers, 2017 to 2025). "To do this, we crossed the zebrafish and mouse models of Rnpc3 deficiency onto a variety of constitutive and inducible tumour-prone backgrounds." (PMID 40624356, 2025). "Histological examination of the lungs 90 d after AdCre delivery revealed a significant reduction in the tumour area and the number of AAH lesions in cells harbouring recombined Rnpc3lox/lox;KrasG12D alleles, compared to cells containing Rnpc3+/+;KrasG12D alleles (Fig. EV2A–D)." (PMID 40624356, 2025). "In addition, survival-related AS events might be involved in tumor-related pathways including base excision repair and pyrimidine metabolism pathways, and some splicing factors might be correlated with prognosis-related AS events, including SPEN, SF3B5, RNPC3, LUC7L3, SRSF11 and PRPF38B." (PMID 34001978, 2021).
RNPC3 also shares sentences with these, for which no sentence is quoted: infection (51 papers); systemic lupus erythematosus (27); influenza (22); viral infection (21); neurodegenerative disease (16); mixed connective tissue disease (13); amyotrophic lateral sclerosis (10); autoimmune disease (8); frontotemporal dementia (7); breast carcinoma (5); lupus nephritis (5); myositis (5); scleroderma (5); connective tissue disease (4); glioblastoma (4); polymyositis (4); pulmonary arterial hypertension (4); spinal muscular atrophy (4); COVID-19 (3); Sjogren syndrome (3); co-infection (2); colorectal cancer (2); dermatomyositis (2); glioma (2); hepatocellular carcinoma (2); HIV-1 infection (2); liver disease (2); myelogenous leukemia (2); myopathies (2); proteinopathies (2).
A further 81 diseases each share a sentence with RNPC3 in 2 papers or fewer.